CHGA (chromogranin A)
Diseases named in the same sentence as CHGA in open-access papers (continued):
Sharing a sentence is not in itself a finding about the gene and the disease.
prostate carcinoma (44 papers, 2004 to 2026). A carcinoma that arises from epithelial cells of the prostate gland. "In silico analysis of FYN expression in prostate cancer cell line databases revealed an association with the expression of neuroendocrine (NE) markers such as CHGA, CD44, CD56, and SYP." (PMID 26624980, 2015). "This study was designed to evaluate the prognostic significance of focal chromogranin A (cgA) expression in prostate cancer in a series of cases with autopsy-verified cause of death." (PMID 20535283, 2010). "Increased levels of ChgA in serum have been associated with poor prognosis/shortened survival for prostate cancer patients." (PMID 17173689, 2006). "ChgA signals have been linked to tumour aggressiveness in prostate cancer, where the presence of proteins/hormones produced from neuroendocrine cells may act as growth factors contributing to paracrine effects on surrounding stromal cells." (PMID 26862851, 2016). "There are discrepancies between the results of different studies regarding the prognostic role of circulating Chromogranin A (CgA) in prostate cancer." (PMID 39975592, 2025). "Neuroendocrine differentiation (NED) characterized by the expression of neuroendocrine markers, such as chromogranin A (CgA), is frequently observed in advanced prostate cancer (PCa), the prognostic significance of which is still controversial." (PMID 37240468, 2023). "Further data were obtained from PubMed and Embase databases by searches using keywords, including chromogranin A and prostate cancer." (PMID 36527470, 2023). "We retrospectively reviewed all 8,194 prostate cancer cases with available immunohistochemistry reports and found 2.3% (n = 189) with any one of the NE markers (CHGA, SYP, and NCAM1) being positive in at least 5% of epithelial cells." (PMID 36033483, 2022). "Almost all prostate cancers show focal neuroendocrine differentiation, but about 5–10% of patients with PCa, have a large number of clustered NE cells that are detected by chromogranin A immunostaining." (PMID 36551525, 2022). "Recently, CHGA has been proposed as an early diagnosis biomarker for gastric cancer, prostate cancer, and pancreatic neuroendocrine tumors." (PMID 34868990, 2021). "Recently, CHGA has been approved as an early diagnosis biomarker for gastric cancer, prostate cancer, and pancreatic neuroendocrine tumors." (PMID 31207989, 2019). "NED was determined by Chromogranin A expression on immunostains from a tissue microarray of 119 nodal positive, hormone treatment-naïve prostate cancer patients who underwent radical prostatectomy and extended lymphadenectomy." (PMID 28788048, 2017). "In prostatic carcinoma, during neuroendocrine differentiation prostate cancer cells shift to neuroendocrine-like cells, characterized for expressing typical neuroendocrine markers (e.g. chromogranin A and neuron specific enolase)." (PMID 28430640, 2017). "These analyses also confirmed that the EBV- PDX were typically prostate cancer with some neuroendocrine features; such as Chromogranin A expression, observed in xenograft H149." (PMID 29145505, 2017). "52, however, demonstrated a correlation between high Gleason score and positivity for chromogranin A in prostate cancer bone metastases and with poor outcome." (PMID 26765317, 2016). "NeuroD1 was previously shown to be expressed in aggressive prostate cancer cell lines and prostate cancer samples, although co-expression with chromogranin A was found only rarely." (PMID 24884804, 2014). "For instance, in prostate cancer, CHGA is considered an important biomarker." (PMID 41372957, 2025). "Therefore, we conducted a meta-analysis of the available findings to explore the value of circulating Chromogranin A in the prognosis of prostate cancer." (PMID 39975592, 2025). "Recently, elevated CHGA levels were also observed in other cancers, such as breast cancer, thyroid cancer, pancreatic cancer, hepatocellular carcinoma, gastric cancer, colon cancer and prostate cancer." (PMID 37246623, 2023).
prostate carcinoma (continued). "We then reviewed 8,194 prostate cancer cases with available immunohistochemistry reports and found 2.3% cases (n = 189) that showed at least one of the NE markers (chromogranin A, synaptophysin, and neural cell adhesion molecule 1) being positive in at least 5% of epithelial cells." (PMID 36033483, 2022). "Interestingly, another pro-inflammatory marker, Il-6, was found to significantly increase the expression of CHGA in prostate cancer cells." (PMID 34620125, 2021). "Here, we demonstrated that TNFAIP8 expression induced expression of the NED biomarkers chromogranin A and synaptophysin in prostate cancer cells; however, the exact mechanism by which TNFAIP8 induces NED in prostate cancer cells remains unclear." (PMID 29928491, 2018). "Interestingly, PEG10 overexpression also correlated with expression of chromogranin A and synaptophysin, markers for neuroendocrine prostate cancer, a type of treatment-resistant prostate cancer." (PMID 29245927, 2017). "Conventional human prostate cancer cells include malignant cells of luminal, basal or neuroendocrine origin at various proportions and unlike the ChgA- luminal cancer cells, tumor cells of neuroendocrine origin are ChgA+." (PMID 21241512, 2011). "In addition to morphological characteristics, transdifferentiated NE-like prostate cancer cells are defined by the expression of a number of neurosecretory products including chromogranin A (CgA) and neuron-specific enolase (NSE)." (PMID 19956567, 2009). "Prostate cancer with neuroendocrine differentiation is typically defined by the heterogeneous histological expression of several NE markers in at least 5% of epithelial cells, including chromogranin A (CHGA), synaptophysin (SYP), neural cell adhesion molecule 1 (NCAM1), and enolase 2 (ENO2)." (PMID 36033483, 2022). "Our study presents data from multiple prostate cancer patients, demonstrating the CoDuCo assay’s ability to visualize diverse resistance mechanisms, such as neuroendocrine differentiation markers (SYP, CHGA, NCAM1) and AR-V7 expression." (PMID 39550585, 2024). "Neuroendocrine differentiation in prostate cancer typically involves the expression of markers like neuron-specific enolase (NES), chromogranin A (CHGA), P63, and CD56, and usually lacks androgen receptor (AR) expression." (PMID 39301540, 2024). "We transiently expressed ID2 in a panel of prostate cancer cell lines; Western blot analysis showed decreased expression of AR and PSA in LNCAP cells, while the expression of NE markers such as CHGA, ENO2, and SYP was elevated in both LNCAP and PC3 cells." (PMID 38254880, 2024). "The expression of common prostate cancer biomarkers, including AR, AMACR, PSA, PSMA, ERG, and neuroendocrine markers (synaptophysin, chromogranin A and CD56) were continually assessed across PDX generations." (PMID 34413304, 2021). "In addition, consistent with the relationship observed in prostate cancer, ACAA2 mRNA expression also positively correlated with expressions of CHGA and CD56." (PMID 37798372, 2023). "In line with this, serum levels of Chromogranin A are significantly higher in metastatic compared to non-metastatic prostate cancers." (PMID 28788048, 2017). "pS2 expression in prostate cancer significantly correlates with histological grade and the neuroendocrine differentiation, as demonstrated by Chromogranin A expression but not with the clinical stage of the disease." (PMID 15588310, 2004). "Biopsy-confirmed metastatic lesions in the bladder, rectum, and bone were observed with a pathologic diagnosis of prostate cancer with small cell features, which was supported by negative PSA, positive synaptophysin (SYP) and positive chromogranin (CHGA) on biopsy tissue immunohistochemistry (IHC)." (PMID 41542660, 2026).
carcinoid (39 papers, 2010 to 2025). "Basic blood workups like blood counts, electrolytes, liver and kidney function along with plasma chromogranin A measurement are studies indicated in the diagnostic process and follow-up of carcinoids." (PMID 39583358, 2024). "For example, c-kit (CD117) or DOG1 is present in GISTs; desmin in leiomyomas; S-100 in schwannomas; smooth muscle actin in glomus tumors; anaplastic lymphoma kinase in inflammatory myofibroblastic tumors; and chromogranin A and synaptophysin in carcinoids." (PMID 38983989, 2024). "Histopathological examination confirmed a diagnosis of Grade 1 NET (typical carcinoid), supported by elevated levels of Synaptophysin and Chromogranin A on immunohistochemistry." (PMID 39268308, 2024). "The final histopathological diagnosis was a typical carcinoid with positive chromogranin A, synaptophysin, and CD56, a Ki-67 labeling index of 5 %, and pathological stage IA3 with T1cN0M0, which was consistent with the intraoperative diagnosis." (PMID 39427400, 2024). "Carcinoids are consistently and diffusely positive for all standard NE markers (synaptophysin, chromogranin A, CD56) and INSM1." (PMID 34663914, 2022). "While virtually all carcinoids are positive for synaptophysin and chromogranin A, their expression is highly variable in NECs." (PMID 34663914, 2022). "As expected, immunohistochemical evaluation confirms the duality of the disease, with expression of specific markers both of thyroid (thyroglobulin, TTF1, calcitonin) and carcinoid (chromogranin A, synaptophysin, NSE and CD56)." (PMID 35528006, 2022). "Immunohistochemical stains were consistent with the diagnosis of carcinoid tumor, with the majority of the cases presenting strong immunoreactivity for synaptophysin, chromogranin A, NCAM, and somatostatin receptor type 2." (PMID 25685590, 2015). "Pathological examinations revealed a cellular arrangement specific to carcinoid tumor and positive for chromogranin A, neural cell adhesion molecule, and somatostatin receptor type 2." (PMID 25685590, 2015). "Plasma chromogranin A, commonly used for the clinical monitoring of NETs, was normal in Case 1 after resection of the carcinoid tumor and elevated in Case 2 with residual tumor and proton pump inhibitor therapy." (PMID 26798346, 2015). "In the smaller carcinoids, expression of the neuroendocrine markers synaptophysin and chromogranin A was higher, but of TTF1 lower in comparison to LCNEC/SCLC." (PMID 25884169, 2015). "Carcinoids were smaller in size and had higher synaptophysin and chromogranin A, but lower TTF-1 expressions." (PMID 25884169, 2015). "Serum Chromogranin A level is elevated in well-differentiated carcinoid tumors and correlates with tumor burden." (PMID 26221561, 2015). "Typical and atypical carcinoids are characterized by a tumor size >5 mm with carcinoid morphology and immunohistochemical expression of the cell markers chromogranin A and synaptophysin." (PMID 26798346, 2015). "Immunohistochemistry of the duodenal biopsy was positive for synaptophysin and chromogranin-A; consistent with the diagnosis of stage I carcinoid tumor." (PMID 29147314, 2012). "His cells were positive for chromogranin A and synaptophysin, and a diagnosis of "typical" carcinoid of the gallbladder was made." (PMID 21801379, 2011). "From histological analysis, Soga found that 100% of typical carcinoid tumors stain positive for chromogranin A and 93.8% of them stain positive for NSE." (PMID 20175936, 2010). "Laboratory testing was positive for elevated serum carcinoembryonic antigen and the neuroendocrine marker chromogranin A. Serum markers of carcinoid, medullary thyroid carcinoma, and pheochromocytoma were in the normal range." (PMID 20807418, 2010).
carcinoid (continued). "Subsequent investigations, including immunohistochemical and ultrastructural studies, proposed a unified origin, showing co-expression of thyroid markers (such as TTF-1 and thyroglobulin) and neuroendocrine markers (synaptophysin, chromogranin-A) in the carcinoid areas or transitional zones." (PMID 40428242, 2025). "Serum chromogranin A (CgA) has been the most widely used biomarker in detecting carcinoid tumors." (PMID 36903295, 2023). "Carcinoid tumors stain positively for keratin 18, chromogranin A, and synaptophysin." (PMID 23691399, 2013). "Carcinoids are often confused with glomus tumors since they have a similar morphology, although by immunostaining carcinoids, but not glomus tumors, are positive for cytokeratin and neuroendocrine markers such as chromogranin A and synaptophysin." (PMID 23050181, 2012). "Carcinoid tumors are a histological subtype of well differentiated, low to intermediate grade, slow-growing neuroendocrine malignancies capable of secreting bioactive peptides, such as 5-hydroxytryptamine (5-HT, serotonin), chromogranin-A and chromogranin-C." (PMID 29147314, 2012). "Once CHD is diagnosed, patients should be evaluated every 6–12 months for progression with TTE, NT-pro-BNP, chromogranin A, and urinary 5-HIAA levels to assess for valvular disease, heart failure, and recurrence or worsening of carcinoid malignancy." (PMID 37277819, 2023). "With NE morphology, or suspected NE morphology, it would be possible to diagnose HGNET or carcinoid using a combination of classic NE markers (CD56, synaptophysin, and chromogranin A) and Ki-67." (PMID 34829292, 2021). "Immunoreactivity for chromogranin A, synaptophysin, TTF-1, and pan-cytokeratins AE1–3 was documented in carcinoid component, while adenocarcinomatous component was positive only for TTF-1 and cytokeratins." (PMID 34926584, 2021). "The serum chromogranin A and urinary 5-HIAA concentrations have been the gold standard biomarkers for the identification and follow-up of carcinoids." (PMID 33108599, 2020). "Carcinoid tumors with clear or eosinophilic cell components usually stain positive for chromogranin A, synaptophysin, and CD56, while ACC stains negative for these markers." (PMID 36820581, 2023). "Immunoreactivity for chromogranin A, synaptophysin, TTF-1, and pan-cytokeratins (AE1-3 clone) was observed in carcinoid component, while glandular component was positive only for TTF-1 and cytokeratins; cytokeratin 7 was selectively expressed in the adenocarcinomatous component." (PMID 34926584, 2021). "However, carcinoid, but not glomus, tumors are positive for cytokeratin and neuroendocrine markers such as chromogranin A and synaptophysin." (PMID 24386948, 2014). "Carcinoids often express neurosecretory markers, including neuron specific enolase, CD56, chromogranin A and synaptophysin, whereas ACCs do not express such biomarkers." (PMID 25013491, 2014). "In contrast, the carcinoid was focally interspersed positive for TTF-1, patchy positive for CDX-2 and PAX-8, and CD56 (basal and cytoplasmic), strongly positive for synaptophysin, and negative for GATA-3, calretinin, and chromogranin-A." (PMID 40428242, 2025). "Whitish/brownish lobulated tumors corresponded to typical carcinoids (less than 2 mitoses/2 mm2 and without necrosis); polygonal/elongated cells under lobular pattern expressed CD56, chromogranin A, synaptophysin, and CK7; Ki-67 positivity was between 1 and 3%." (PMID 26613062, 2015).
pheochromocytoma (39 papers, 1996 to 2026). "However, normal chromogranin A levels in this scenario prompted reconsideration of the diagnosis, suggesting a paraneoplastic cause unrelated to a classic pheochromocytoma." (PMID 40666573, 2025). "Initial suspicion was for pheochromocytoma, but normal chromogranin A levels suggested a paraneoplastic phenomenon." (PMID 40666573, 2025). "Testing for plasma-free metanephrines or fractionated metanephrines in 24-hour urine is highly sensitive for pheochromocytoma, and chromogranin A is frequently elevated in most catecholamine-producing tumors, boasting a negative predictive value of up to 95%." (PMID 40666573, 2025). "Measurement of plasma metanephrines and chromogranin A levels aids in distinguishing NSCLC-related catecholamine secretion from pheochromocytoma." (PMID 40666573, 2025). "Histopathology confirmed two separate malignancies, with chromogranin A positivity supporting pheochromocytoma and CD20 positivity confirming B-cell lymphoma." (PMID 41227489, 2025). "Biochemical results of catecholamines and their metabolites, chromogranin A, plasma glucose and HbA1c in patients diagnosed with pheochromocytomas or paragangliomas, also comparing females and males." (PMID 39917539, 2025). "Histopathology showed a cell rich tumour, surrounded by normal adrenal tissue and with immunohistochemistry positive for chromogranin A, consistent with pheochromocytoma, probably emanating from the remains of the previously operated right adrenal." (PMID 40887494, 2025). "Standard neuroendocrine markers include chromogranin A and synaptophysin, which are typically positive in pheochromocytomas, confirming neuroendocrine differentiation." (PMID 40709162, 2025). "Elevated serum chromogranin A levels facilitated the diagnosis of pheochromocytoma in these patients and informed our caution regarding potential hypertension attacks during surgery." (PMID 38747189, 2024). "Chromogranin A, an essential protein marker for pheochromocytomas, should be assayed preoperatively in patients with normal preoperative plasma or urinary levels of metanephrine and normetanephrine." (PMID 38747189, 2024). "The expression of chromogranin A and synaptophysin were consistent with the diagnosis of pheochromocytoma." (PMID 39822445, 2024). "Histopathology with H&E stain showed hyperchromatic, pleomorphic chromaffin cells and diffuse immunoreactivity for chromogranin A, consistent with pheochromocytoma/paraganglioma." (PMID 39822445, 2024). "Immunohistochemical examination of the tumor showed chromogranin A positivity leading to the diagnosis of left pheochromocytoma." (PMID 36797699, 2023). "Pheochromocytoma cells also express higher levels of the DCG assembly protein Chromogranin A in response to secretion." (PMID 27727275, 2016). "We have established a human pheochromocytoma precursor cell line that expresses the neuroendocrine marker, chromogranin A, when differentiated in the presence of bone morphogenic protein 4 (BMP4), nerve growth factor (NGF), and dexamethasone." (PMID 23785438, 2013). "Both Chromogranin A and synaptophysin were strongly and diffusely positive in the pheochromocytoma/paraganglioma cells." (PMID 23587063, 2013). "During follow-up, the course of chromogranin A was found to parallel that of tumour burden and/or 24-hour urinary metanephrine in 5 phaeochromocytoma patients." (PMID 11259096, 2001). "The structure of circulating chromogranin A (CgA) of phaeochromocytoma patients was characterised and compared with that of CgA extracted from tumours." (PMID 8611427, 1996). "Comprehensive biochemical evaluation was normal: 24 h urinary 5-hydroxyindoleacetic acid 6 mg/d (normal 0-15), chromogranin A 50 ng/mL (normal 0-187), plasma metanephrine 0.12 nmol/L (normal 0.00-0.49), and normetanephrine 0.68 nmol/L (normal 0.00-0.89), excluding pheochromocytoma." (PMID 41704395, 2026).